CFL1 (cofilin 1)
Diseases named in the same sentence as CFL1 in open-access papers (continued):
Sharing a sentence is not in itself a finding about the gene and the disease.
head and neck squamous cell carcinoma (2 papers, 2022 to 2023). A squamous cell carcinoma that arises from any of the following anatomic sites: lip and oral cavity, nasal cavity, paranasal sinuses, pharynx, larynx, and salivary glands. "Actin-binding proteins, including cofilin (CFL1), profilin 1 (PFN1), and adenylate cyclase-associated protein 1 (CAP1), are thought to be involved in tumor cell motility and metastasis, specifically in head and neck squamous cell carcinoma (HNSCC)." (PMID 37226274, 2022).
HIV-1 infection (2 papers, 2022 to 2023). The type species of lentivirus and the etiologic agent of acquired immunodeficiency syndrome (AIDS). "Contrary to the previous results for the UPR and IFN-IP markers, there was a significant decrease average of a 0.59-fold change in total cofilin-1 vs. the control for HIV-1 infection." (PMID 36992512, 2023). "Herein, we studied in vitro effects of E2 on HIV-1 infection and on CFL1 expression to gain insight into the mechanism of HIV-1 inhibition by E2." (PMID 35418661, 2022). "In resting CD4+ T cells, which are resistant to HIV-1 infection, CFL1 is largely phosphorylated hindering viral post-entry migration." (PMID 35418661, 2022). "This study was designed to explore the role of CFL1 in E2-mediated effects on HIV-1 infection in PBMCs and endocervical mucosa." (PMID 35418661, 2022). "We hypothesized that E2 would inhibit in vitro HIV-1 infection, induce CFL1 gene expression, and increase CFL1 total protein and pCFL1 expression." (PMID 35418661, 2022). "Given the knowledge of HIV-1 infection, this study investigated the role of PSP in regulating the ADF cofilin-1 required for viral entry through the IFN-IP and UPR signaling." (PMID 36992512, 2023).
Huntington disease (2 papers, 2021 to 2023). Huntington disease (HD) is a rare neurodegenerative disorder of the central nervous system characterized by unwanted choreatic movements, behavioral and psychiatric disturbances and dementia. "Finally, based on pathway, three genes were associated with cytoskeletal regulation by Rho GTPase pathway (ACTB, PFN1 and CFL1) while two genes were associated each with glycolysis (GAPDH and PGK1) and Huntington disease (GAPDH and ACTB)." (PMID 34681026, 2021).
ischemia (2 papers, 2018 to 2024). A hypoperfusion of the BLOOD through an organ or tissue caused by a PATHOLOGIC CONSTRICTION or obstruction of its BLOOD VESSELS, or an absence of BLOOD CIRCULATION. "The magnitude of this reduction appeared to be less than in the cell cultures, possibly because of signal from tissue above and below the selected neurites (despite confocal imaging) or partial re-phosphorylation of free cofilin-1 in the 24 hour interval between ischemia and brain harvest." (PMID 30325927, 2018).
metastatic melanoma (2 papers, 2018 to 2021). A melanoma that has spread from its primary site to another anatomic site. "In metastatic melanoma, there is a significant loss of PLXNC1, which results in an enhanced activation of CFL1 and acquisition of a metastatic phenotype by cancer cells." (PMID 35008571, 2021). "Regarding cofilin-1 intracellular localization, we demonstrated not only the increase of total levels of this protein, but also its higher expression in the nucleus of metastatic melanoma cells and MM with BI>2." (PMID 29844875, 2018).
oral cancers (2 papers, 2012 to 2021). "Cofilin-1 knockdown by siRNA significantly inhibited oral cancer cell invasion across Matrigel in vitro." (PMID 23227181, 2012). "Besides the identification of several proteins not yet described as deregulated in oral carcinomas, the present study demonstrated for the first time the role of cofilin-1 in modulating cell invasion in oral carcinomas." (PMID 23227181, 2012). "Besides the identification of several proteins not yet described as deregulated in oral cancer, the present study demonstrated for the first time the role of cofilin-1 in modulating OSCC cell invasion, adding new data that may be useful for predicting aggressive phenotype in OSCC." (PMID 23227181, 2012).
spina bifida (2 papers, 2007). A congenital neural tube defect in which vertebrae are not fully formed. "The sequence variation of human CFL1 gene is a genetic modifier for spina bifida risk in this California population." (PMID 17352815, 2007). "We also evaluated the association between individual CFL1 SNP marker genotypes and spina bifida risk in the overall population, as well as in the two major ethnic subpopulations, non-Hispanic white and Hispanic white." (PMID 17352815, 2007). "In this study, we re-sequenced the genomic region on human chromosome 11 which encompasses the CFL1 gene, and tested the hypothesis that genetic polymorphisms in human CFL1 gene may modify human spina bifida risk." (PMID 17352815, 2007). "Having re-sequenced the human CFL1 gene and identified five common single nucleotide polymorphisms (SNPs) in our target population, we investigated whether there existed a possible association between the genetic variations of the CFL1 gene and risk of spina bifida." (PMID 17352815, 2007).
synucleinopathies (2 papers, 2020 to 2022). "Here we used a mouse model of synucleinopathy to test the effect of cofilin 1 on the spreading of α-synuclein pathology." (PMID 35013321, 2022).
triple-negative breast carcinoma (2 papers, 2022 to 2025). An invasive breast carcinoma which is negative for expression of estrogen receptor (ER), progesterone receptor (PR), and human epidermal growth factor receptor 2 (HER2). "•Cofilin-1 is involved in promoting triple negative breast cancer metastasis." (PMID 34678587, 2022).
viral infection (2 papers, 2017 to 2023). "The unique properties of PKR range from an immune response against viral infection to a survival regulator, but most importantly it has been linked to the phosphorylation of cofilin-1 (Ser3)." (PMID 36992512, 2023). "Viral infection also demonstrated an increase of a 2.65-fold average of p-cofilin-1 compared to its total counterpart." (PMID 36992512, 2023). "Equivalently to total cofilin-1 expression, viral infection received a significant decrease of 0.67-fold for cytosolic gelsolin." (PMID 36992512, 2023).
benign prostatic hyperplasia (1 paper, 2025). A non-cancerous nodular enlargement of the prostate gland. "Differently, the cytoskeletal protein CFL1 was identified in both benign prostatic hyperplasia and PCa tissues as a histopathological biomarker candidate to avoid the misdiagnosis." (PMID 40136513, 2025).
bipolar disorder (1 paper, 2014). A disorder of the brain that causes unusual shifts in mood, energy, activity levels and the ability to carry out day-to-day tasks. "Patients with bipolar disorder also showed a nonsignificant trend in the same direction, and it was close to significance (P = 0.05) for the CFL1-normalized ADAR2 expression level." (PMID 24443933, 2014).
bronchopulmonary dysplasia (1 paper, 2021). Bronchopulmonary dysplasia is a chronic respiratory disease that results from complications related to lung injury during the treatment of infant acute respiratory distress syndrome in low-birth-weight premature infants or from abnormal lung development in older infants. "Studies have examined lower profilin-1 and elevated cofilin-1 levels observed in infant bronchopulmonary dysplasia (BPD) tissue." (PMID 34194957, 2021).
cardiomyopathy (1 paper, 2022). A disease of the heart muscle or myocardium proper. "Therefore, we wondered whether MRTF-A altered localization due to increased phospho(T25)-cofilin-1 expression might cause impaired SRF activity in LMNA-induced cardiomyopathy." (PMID 36550158, 2022). "Here, we show that in muscle cells carrying a cardiomyopathy-causing LMNA mutation, phospho(T25)-cofilin-1 binds to myocardin-related transcription factor A (MRTF-A) in the cytoplasm, thus preventing the stimulation of serum response factor (SRF) in the nucleus." (PMID 36550158, 2022). "Together, these results show that the expression of cofilin-1 phosphorylated on T25 affects SRF-mediated gene expression and leads to cardiomyopathy." (PMID 36550158, 2022).
cervical cancer (1 paper, 2024). A primary or metastatic malignant neoplasm involving the cervix. "The results suggest that LIMK1 promotes the invasion, metastasis, and proliferation of cervical cancer cells and promotes cervical cancer development by regulating the oxidative stress/SRC-mediated p-FAK/p-ROCK1/2/p-Cofilin-1 pathway." (PMID 38975937, 2024). "In summary, LIMK1 promotes F-actin expression and cervical cancer development by regulating the oxidative stress/src-mediated p-FAK/p-ROCK1/2/p-Cofilin-1 pathway." (PMID 38975937, 2024). "In conclusion, our study reveals the mechanism of action of LIMK1 in cervical cancer progression, suggesting that LIMK1 can promote the development of cervical cancer by regulating the oxidative stress/Src-mediated p-FAK/p-ROCK1/2/p-Cofilin-1 pathway." (PMID 38975937, 2024). "Studies have also shown that Cofilin-1 affects the chemical sensitivity of cervical cancer." (PMID 38975937, 2024).
cholangiocarcinoma (1 paper, 2020). A carcinoma that arises from the intrahepatic biliary tree (intrahepatic cholangiocarcinoma) or from the junction, or adjacent to the junction, of the right and left hepatic ducts (hilar cholangiocarcinoma). "Interrogation of the TCGA datasets using cBioPortal indicated that MCL1, SRC and CFL1 are expressed among cholangiocarcinomas and PDACs to a similar extent to that of invasive breast carcinomas." (PMID 31735913, 2020).
chronic obstructive pulmonary disease (1 paper, 2023). A chronic and progressive lung disorder characterized by the loss of elasticity of the bronchial tree and the air sacs, destruction of the air sacs wall, thickening of the bronchial wall, and mucous accumulation in the bronchial tree. "Notably, loss of cofilin-1, an actin-severing protein, occurs in chronically injured epithelium, as seen with recurrent insults that result in chronic obstructive pulmonary disease (COPD)." (PMID 37504520, 2023).
chronic periodontitis (1 paper, 2013). A chronic inflammatory process that affects the tissues that surround and support the teeth. "In addition, other GCF proteins were also identified previously and confirmed in the current investigation as alpha 1 antitrypsin, cofilin-1, profilin 1, cathelicidin antimicrobial peptide, and heat shock protein in chronic periodontitis subjects." (PMID 24098404, 2013).
Cognitive impairment (1 paper, 2023). Abnormal cognition is characterized by deficits in thinking, reasoning, or remembering. "Bidirectional shifts in phosphorylated/inactive vs. dephosphorylated/active forms of cofilin 1 in the brain critically contribute to the loss of dendritic spines and synapses underlying the AD-associated cognitive impairment." (PMID 36839831, 2023).
colon adenocarcinoma (1 paper, 2018). "In this regard, cofilin-1 overexpression was associated with increased migration in colon adenocarcinoma cells and has been used as poor prognosis marker, related to metastasis, in non-small cell lung cancer patients and invasive breast cancer cells." (PMID 29844875, 2018). "Furthermore, a partial nuclear translocation of phosphorylated/inactive cofilin-1 was observed in colon adenocarcinoma cell lines characterized by an invasive phenotype." (PMID 29844875, 2018).
cryptococcosis (1 paper, 2012). An acute or chronic, localized or disseminated infection by Cryptococcus neoformans. "Unlike Znf2, overexpression of CFL1 attenuates but does not abolish Cryptococcus virulence in the murine model of cryptococcosis." (PMID 22737071, 2012).
dementia (1 paper, 2023). Loss of intellectual abilities interfering with an individual's social and occupational functions. "Dysregulation of p-cofilin-1/cofilin-1 levels in neurons occurred not only in AD, but also with subsequent dementia in other neurological disorders and normal aging." (PMID 37443762, 2023).
Emery-Dreifuss muscular dystrophy (1 paper, 2023). Emery-Dreifuss muscular dystrophy (EDMD) is characterized by muscular weakness and atrophy, with early joint contractures and cardiomyopathy. "Cofilin-1 is normally cleared by the Ub-proteasomal system after muscle differentiation, but failure to clear cofilin-1 from mature muscle causes sarcomere disorganization and impaired force generation thereby enhancing phenotypes in Emery-Dreifuss muscular dystrophy." (PMID 37869480, 2023).
folate deficiency (1 paper, 2020). A nutritional condition produced by a deficiency of FOLIC ACID in the diet. "In an 2DGE-MS-based study of rat livers, PRDX6 and GPX1 are reported to be elevated while cofilin (CFL1) is reported to be depleted under folate deficiency." (PMID 32863845, 2020).
follicular thyroid cancer (1 paper, 2018). "Future experiments will be necessary to study cofilin-1 in follicular thyroid cancer in detail." (PMID 30545079, 2018).
gastric tumor (1 paper, 2020). "Therefore, it was concluded that CFL1 promotes the EMT process and gastric tumor cell invasion through cytoskeletal rearrangement." (PMID 32467737, 2020).
head-neck cancer (1 paper, 2017). "Co-expression analysis revealed that CAP1 was coexpressed with TUBA1B both in pancreatic and head-neck cancer, as well as with CFL1, CFL2, DSTN, and ROBO1, according to STRING analysis." (PMID 28423713, 2017). "The co-expression analysis revealed that CAP1 was coexpressed with TUBA1B in pancreatic and head-neck cancer, as well as with CFL1, CFL2, DSTN, ACTB, ACTG1, and ROBO1, according to the STRING analysis." (PMID 28423713, 2017).
Hypertension (1 paper, 2021). The presence of chronic increased pressure in the systemic arterial system. "We may speculate that this increased cofilin-1 expression could be a compensatory mechanism against aortic stiffening in SHRc, induced by high activity of the RhoA/Rho-kinase pathway, observed in hypertension." (PMID 33679438, 2021).
ischemic stroke (1 paper, 2021). A stroke disorder caused by obstruction of blood flow to the brain, due to thrombotic (local blood clot formation) or embolic (due to a blood clot or other material traveling from another site) event. "Recent studies have emphasized that cofilin-1 is involved in the harmful neuronal processes of ischemic stroke, especially in the penumbra." (PMID 33777942, 2021).
keratoconus (1 paper, 2009). A degenerative, structural disorder of the eye, characterized by a cone-shaped protrusion of the cornea. "CFL1 was also a gene whose expression was increased in keratoconus." (PMID 19956410, 2009). "However, we assessed the expression of eight genes in more detail by employing RT-PCR and real-time PCR, which confirmed the overexpression of BMP4, CFL1, and MRVI1, and the underexpression of ACTA2, GRCC10, TIMP3, TIMP1, and SSTR1 in keratoconus." (PMID 19956410, 2009).
kidney damage (1 paper, 2024). "We confirmed the influence of several known NEMG on kidney disease and function and found novel associations for SLC39A13, CFL1, ACP2 or ATP5G1 with serum variables and kidney damage, and for SLC4A1, NUP210 and MYH14 with ESKD." (PMID 38858654, 2024).
kidney injury (1 paper, 2023). Trauma to the kidney. "Moreover, urinary Cofilin-1 is significantly upregulated in AKI patients, and in cultured kidney injury models." (PMID 37548903, 2023).
kidney stones (1 paper, 2024). "Up-regulation of cofilin-1 in HK-2 cells treated with calcium oxalate monohydrate, the major crystalline composition of most kidney stones, suggests it may play a key role in response to the COM crystals adhesion." (PMID 38858654, 2024).
MALT lymphoma (1 paper, 2017). An indolent, extranodal type of non-Hodgkin lymphoma composed of small B-lymphocytes (centrocyte-like cells). "Since no commercial ELISA kit is available for detecting the autoantibodies against cofilin-1, alpha-enolase or RGI2, we have developed respective ELISAs to quantify their levels in saliva samples of patients with pSS or pSS/MALT lymphoma." (PMID 28404907, 2017). "It is possible that upregulation of anti-alpha-enolase, anti-cofilin-1 and anti-RGI2 may promote the development of pSS and pSS/MALT lymphoma, but further studies are certainly warranted to elucidate the potential molecular mechanisms." (PMID 28404907, 2017).
mammary adenocarcinoma (1 paper, 2013). "Here we focused on the roles of ADF and cofilin-1 individually in the development of polarized migration of rat mammary adenocarcinoma (MTLn3) cells, which express nearly equal amounts of each protein." (PMID 24093776, 2013).
muscular dystrophy (1 paper, 2021). Muscular dystrophy (MD) refers to a group of more than 30 genetic diseases characterized by progressive weakness and degeneration of the skeletal muscles that control movement. "Similar pathogenic mechanism of cofilin-1-mediated modulation of sarcomeric actin dynamics may play a role in other muscular dystrophies, in which there appears to be abnormal activation of ERK1/2 signaling." (PMID 34433058, 2021). "We further demonstrated that muscular dystrophy is associated with muscle cofilin-1 activation, which generated sarcomere disruption and alteration of force production, suggesting that cofilin-1 overexpression is a pathological event in muscular dystrophy caused by LMNA mutations." (PMID 34433058, 2021). "This tight regulation of phospho(T25)-cofilin-1 protein levels by ERK1/2 signaling is important for the maintenance of sarcomere structure and force generation, which participate in the development of muscular dystrophy caused by LMNA mutations." (PMID 34433058, 2021).
myocardial infarction (1 paper, 2024). Gross necrosis of the myocardium, as a result of interruption of the blood supply to the area, as in coronary thrombosis. "The expression level of CRSP2, HSP27, IL-8, Cofilin-1, and HSP90 in the LV tissues following coronary artery bypass graft (CABG) and myocardial infarction (MI) and CF cells followed the screening profile derived from the MS/MS findings." (PMID 39302489, 2024).
neuroblastoma (1 paper, 2024). Neuroblastoma (NB) is the most common solid, extracranial childhood tumor. "We further verified the effect of α-synuclein fibrils on cofilin-1 in human neuroblastoma cells (SH-SY5Y cells)." (PMID 39224576, 2024).
osteosarcoma (1 paper, 2022). A usually aggressive malignant bone-forming mesenchymal neoplasm, predominantly affecting adolescents and young adults. "Specifically, cofilin-1 mRNA has been reported to be increased in various malignant cells such as adenocarcinomas, osteosarcoma, and lymphoid tissue, in comparison to control tissue." (PMID 34678587, 2022).
ovarian tumor (1 paper, 2019). "In another word, the expression level of cofilin-1 in the ovarian tumor was elevated in low stages (I, II) compared to that in high stages (III, IV)." (PMID 31700829, 2019).
pneumonia (1 paper, 2019). An acute, acute and chronic, or chronic inflammation focally or diffusely affecting the lung parenchyma, caused by an infection in one or both of the lungs (by bacteria, viruses, fungi, or mycoplasma.). "Glyceraldehyde 3‐phosphate dehydrogenase (GAPDH; degree = 13, closeness centrality = 0.54), Nucleoside diphosphate kinase B (NME2; degree = 6, closeness centrality = 0.44) and Cofilin‐1 (CFL1; degree = 6, closeness centrality = 0.42) were the three hub proteins of the pneumonia‐specific PPI network." (PMID 30761252, 2019).
prion disease (1 paper, 2015). A transmissible disease that is caused by a protein that is able to induce abnormal folding of normal cellular proteins, leading to characteristic spongiform brain changes, which are associated with neuronal loss without an inflammatory response. "Similarly, GFAP, tubulin, peroxiredoxin 1, cofilin-1, and alpha/gamma enolase are selectively citrullinated in prion disease." (PMID 26441823, 2015).